BRCA2 (BRCA2 DNA repair associated)
Diseases named in the same sentence as BRCA2 in open-access papers (continued):
Sharing a sentence is not in itself a finding about the gene and the disease.
breast cancer (continued). "Women were defined as high risk if they had a germline mutation that greatly increases lifetime risk of a breast cancer diagnosis including BRCA1, BRCA2 and PALB2 (refs.2,18)." (PMID 35187501, 2021). "Improved predictors for identifying women and families who carry pathogenic variants in breast cancer predisposition genes other than BRCA1 and BRCA2 are urgently needed." (PMID 34887416, 2021). "T he lifetime risk of ovarian and breast cancer (BC) in women with pathogenic variants in BRCA1 and BRCA2 gene is 72% and 69%, 44% and 17%, respectively." (PMID 34627117, 2021). "Studies suggest that patients with pathogenic mutations (such as BRCA1, BRCA2, ATM or CHEK2) are more prone to have axillary metastasis, related to their highly aggressive breast cancers." (PMID 34945851, 2021). "Results of studies about breast cancer risk in women with these mutations by age 70 have been in range of 44 -78% of women with BRCA1 mutations and 31 -56 % with BRCA2 mutations with increased breast cancer." (PMID 34710987, 2021). "A case–control study found evidence for an independent association of PC risk with PGVs in six genes: ATM, BRCA1, BRCA2, CDKN2A, MLH1, and TP5316, five of which (excluding CDKN2A) have a clear link to breast cancer risk." (PMID 34127761, 2021). "In summary, case-control comparisons yielded high estimates of relative risk for breast cancer, and even higher estimates for TNBC, for BRCA1, BRCA2, and PALB2 among both EA and AA women." (PMID 33479248, 2021). "As previously reported, breast cancer is the most common malignancy in individuals with BRCA1 or BRCA2 germline PVs and the ductal histotype was more frequent than others." (PMID 34572941, 2021). "It has been estimated that the average man has less than 1% lifetime risk of developing breast cancer (BC), but for men who harbor a BRCA1- or BRCA2- mutation, this risk amplifies significantly." (PMID 34575694, 2021). "The cumulative risk 20 years after breast cancer diagnosis was estimated to be 40% for BRCA1 carriers and about 26% for BRCA2 carriers." (PMID 34490083, 2021). "The splice-site variant represented a significantly higher proportion of all BRCA2 P/LPVs detected in MBC carriers compared to female breast cancer (FBC) carriers (47.4% vs. 26%, p = 0.049)." (PMID 33891299, 2021). "The phase III BROCADE3 trial compared veliparib plus carboplatin plus paclitaxel versus placebo combined with carboplatin and paclitaxel in patients with HER2-negative advanced breast cancer and a germline BRCA1 or BRCA2 mutation (NCT02163694)." (PMID 33802424, 2021). "We found evidence of association with breast cancer risk for four genes, with estimated adjusted ORs of 5.3 [95% CI: 2.1–16.2] for BRCA1, 4.0 [95% CI: 1.9–9.1] for BRCA2, 3.4 [95% CI: 1.4–8.4] for ATM and 4.3 [95% CI: 1.0–17.0] for PALB2." (PMID 34887416, 2021). "Twenty founder alleles in BRCA1, BRCA2, CHEK2, NBN, PALB2 and RECQL genes are responsible for the majority of hereditary breast cancers in Polish women." (PMID 34461861, 2021). "For a long time, breast cancer was considered a disease with genetic origins, predominantly resulting from mutations in key genes such as BRCA1 and BRCA2." (PMID 34884658, 2021).
breast cancer (continued). "Approximately 3–5% of patients with breast cancer and 8–17% of patients with ovarian cancer can attribute the cancer to germline pathogenic variants in the BRCA1 and BRCA2 genes, which is called the hereditary breast-ovarian cancer (HBOC) syndrome." (PMID 34525964, 2021). "A founder mutation of BRCA1, BRCA2, CHEK2, PALB2 and NBN was found in 13.3% of men with breast cancer in Poland." (PMID 34461861, 2021). "Inherited germline variants in BRCA1 and BRCA2 account for around 2% and 10% of MBC cases, respectively, and the lifetime risk of breast cancer for men harboring BRCA1 and BRCA2 mutations is 1.2% and 6.8%." (PMID 34298749, 2021). "The cumulative breast cancer risk to age 80 years is 72% (95% CI, 65%–79%) for female with BRCA1 mutation and 69% (95% CI, 61%–77%) for female with BRCA2 mutation." (PMID 33996049, 2021). "Loss of heterozygosity (LOH) of the wild-type allele to accompany hereditary pathogenic variants in BRCA1 or BRCA2 is predicted to lead to loss of function (LOF) of these genes and increases genomic instability during breast cancer development." (PMID 34439109, 2021). "The PALB2 (partner and localizer of BRCA2) mutation was found to be associated with an increased risk of breast cancer and one of the most common mutations, after BRCA1 and BRCA2, in non-BRCA1/2 breast cancer patients." (PMID 34439348, 2021). "Our survival analysis in breast cancer patients suggests that tumors with high ALC1 expression combined with low levels of BRCA2 have a poor prognosis." (PMID 33333017, 2021). "Male breast cancer is rare, and they are more often BRCA mutation carriers compared to women, preferably BRCA2 mutations." (PMID 33996049, 2021). "Activation of the TGFβ pathway was shown to result in reduced expression of ATM, BRCA1 and BRCA2 in BRCA-proficient breast cancer cells, and of RAD51 in lung epithelial cells -resulting in suppression of DNA damage repair." (PMID 34871431, 2021). "One study reported a 72% lifetime risk of breast cancer and a 44% lifetime risk of OVCA for females with BRCA1 mutations and lifetime risks of 69% for breast cancer and 17% for OVCA for females with BRCA2 mutations." (PMID 34208188, 2021). "In most other breast cancer genes, including BRCA1 and BRCA2, it is the loss of DNA repair capacity that associates with variant severity." (PMID 34584094, 2021). "Among the identified genes, CFL1 (Gene Entrez ID 1072) and BRCA2 (Gene Entrez ID 675) were validated as the basal and luminal breast cancer gene markers." (PMID 34573857, 2021). "Tumor cells that are defective in either of the breast cancer susceptibility genes (i.e., BRCA1 or BRCA2) are sensitive to the inhibition of PARP1." (PMID 34359565, 2021). "As with cancers of the breast, ovary, and pancreas, germline mutations in BRCA1 and BRCA2 associate with an increased risk of developing PC, and approximately 5% of men with mPC carry inherited pathogenic mutations in these genes." (PMID 34877933, 2021). "The most important of these are the breast cancer susceptibility genes BRCA1 and BRCA2, and ATM and CHK2 are also important risk factors." (PMID 34198652, 2021). "We found that the PRS is associated with contralateral breast cancer risk in both BRCA1 and BRCA2 heterozygotes of European ancestry and that PRS can be used to refine estimates of contralateral breast cancer risks in these women." (PMID 34113011, 2021). "Germline variants in ATM, BRCA1, BRCA2, CHEK2, and PALB2 were associated with a high risk of breast cancer; a more modest risk was associated with BARD1 and RAD51C." (PMID 34445631, 2021).
breast cancer (continued). "This large unique dataset allowed an in-depth investigation of the impact of the type of mutated gene (BRCA1 vs BRCA2) and hormone receptor status on clinical behavior and outcomes of BRCA-mutated breast cancer in young women." (PMID 33579978, 2021). "In comparison to non-carriers, 63% of BRCA1 positive cases reported family history of breast cancer and 56% of BRCA2 cases had family history of other cancers (p = 0.001)." (PMID 34206661, 2021). "BRCA2-selective hypersensitivity of cancer cells towards the WRNi was further recapitulated in the breast cancer cell line MDA-MB-231 and ovarian cancer cell line SKOV-3, suggesting generality of the phenotype." (PMID 34772932, 2021). "In breast cancer, pathogenic or likely pathogenic germline BRCA1 or BRCA2 variants are present in 6.1% of all cases, and 10–20% of triple-negative breast cancer cases." (PMID 34711195, 2021). "L939W reduces interaction with BRCA2, RAD51, XRCC3 and decreases double stranded DNA break initiatedhomologous recombination associated with breast cancer susceptibility." (PMID 34092963, 2021). "One in eight women will be diagnosed with breast cancer in their lifetime, but only 5–10% of these women have a BRCA1 and/or BRCA2 (BReast CAncer) genetic mutation." (PMID 34969949, 2021). "In breast cancer, the germlines BRCA1, BRCA2, as well as somatic BRCA1 were associated with DNA damage/repair, cell cycle, chromosome maintenance, and transcription." (PMID 33525353, 2021). "In women with breast cancer, the prevalence of pathogenic BRCA1/BRCA2 variants is approximately 1 in 33, and almost 1 in 8 if the affected individual is an AYA." (PMID 34771713, 2021). "Of 160 cancers with BRCA1/2 mutations, LOH was detected in 90% cases of BRCA1 positivity and 54% cases of BRCA2 positivity in breast cancer, and in 93% cases of BRCA1 positivity and 84% cases of BRCA2 positivity in ovarian cancer." (PMID 32862296, 2021). "De novo somatic BRCA1/2 mutations in breast cancer are considered to be rare: the prevalence of somatic BRCA1 gene mutations in primary tumors is only 1.55%, and that of somatic BRCA2 gene mutations is 1.68%42." (PMID 33854152, 2021). "A prospective study with 3886 breast cancer patients showed that a cumulative risk was 72% for BRCA1 and 69% for BRCA2 carriers." (PMID 33805996, 2021). "Pathogenic variants in the breast cancer genes of BRCA1, BRCA2, and PALB2 are common causes of breast cancer in Caribbean women." (PMID 33646313, 2021). "It is estimated that 5% to 10% of breast cancer cases are related to inherited predisposition genes, with germline BRCA1 and BRCA2 pathogenic variants (BRCA PV) being the most common." (PMID 35875314, 2021). "Molecular interaction between SeNPs and BRCA2 protein showed good interaction access to exhibit the functions of nanoparticles conveyor in the breast cancer target proteins." (PMID 33441811, 2021). "Two MBC patients had bilateral breast cancer and both were carriers of P/LPVs: one of them BRCA2:c.7806-2A > G and the other BRCA2:c.6445_6446delAT." (PMID 33891299, 2021). "The 5-, 10-, and 15-year cumulative CBC risk of 810 female BRCA1/2 breast cancer patients is 13.7%, 23.8%, and 36.1% for BRCA1 and 12.0%, 18.7%, and 28.5% for BRCA2, respectively." (PMID 32862296, 2021). "In the analyses, 6,591 BRCA1 and 4,208 BRCA2 heterozygotes of European ancestry who had developed an invasive first primary breast cancer before entry in CIMBA were identified." (PMID 34113011, 2021).
breast cancer (continued). "Of breast cancer cases, Breast Cancer Gene 1 (BRCA1) and Breast Cancer Gene 2 (BRCA2) mutations are the most commonly encountered CPGs." (PMID 34070674, 2021). "The cumulative lifetime breast cancer risk was 59.1% (95% CI: 44.1–73.6%) for BRCA1 and 58.3% (95% CI: 43.2–73.0%) for BRCA2 carriers." (PMID 34063308, 2021). "Among these, BRCA1, BRCA2, and PALB2 were still classified as high risk, and ATM, BARD1, CHEK2, and RAD51D were still classified as moderate risk breast cancer susceptibility genes in Chinese women." (PMID 34606182, 2021). "Breast cancer (BC) risk for BRCA1 and BRCA2 mutation carriers varies by genetic and familial factors." (PMID 33597508, 2021). "In ovarian or breast cancer, olaparib resistance is associated with HRR recovery, including the reversal of BRCA2 mutations." (PMID 34066020, 2021). "RRSO before the age of 40 and specifically for breast cancer treatment in BRCA2 should be considered only if recommended by their breast cancer oncologist." (PMID 34565426, 2021). "For BRCA2 carriers, 230 (54.4%) had prior or prospective breast cancer with 179 (42.3%) having chemotherapy." (PMID 33152107, 2021). "Expression of other PARP genes was higher in somatic BRCA1 and BRCA2 carriers in breast cancer, and in gBRCA1, sBRCA1, and gBRCA2 in ovarian cancers." (PMID 33525353, 2021). "We have reported a mean annual rate of incident prospective breast cancers in BRCA1/2 PV carriers of 1.6% (1.55% BRCA2, 1.73% BRCA1), consistent with currently published 69–72% risks by age 80 years when extrapolated over a 50-year risk period." (PMID 34312777, 2021). "In all, 141 women who underwent mastectomy for breast cancer treatment or prevention were included in the study: 74 were positive for BRCA1 mutations and 67 had BRCA2 mutations." (PMID 33649363, 2021). "The cumulative 10-year risk of developing contralateral breast cancer in this cohort was 25%, 95% CI (23.5–26.4%) and 18.8%, 95% CI (17.1–20.5%) for BRCA1 and BRCA2 heterozygotes, respectively." (PMID 34113011, 2021). "PARGi is also synthetically lethal in BRCA1, BRCA2, PALB2, FAM175A and BARD1 deficient breast cancer cells." (PMID 33674744, 2021). "Within the studied breast cancer cohort, 13 pathogenic mutations have been identified: 8 in BRCA1 and 5 in BRCA2 genes." (PMID 34490083, 2021). "The Consortium of Investigators of Modifiers of BRCA1 and BRCA2 (CIMBA), established in 2006, has provided a large number of BRCA mutations related to breast cancer." (PMID 34065872, 2021). "The estimated lifetime breast cancer risk in an individual with PHTS is between 67–85%, similar to that conferred by germline variants in BRCA1/BRCA2." (PMID 34771713, 2021). "It will be important to revisit predictors of survival for women with MRI-detected breast cancer and for women with stage I cancers in both BRCA2 and BRCA1 carriers." (PMID 33597716, 2021). "As the BRCA1 and BRCA2 gene products are involved in homologous recombination, the identification of BRCA1/2-deficient tumors in breast cancer patient implied important treatment connotations." (PMID 33540843, 2021).
breast cancer (continued). "Other examples of biomarkers excluded in this review are the loss of tumor suppressors in cancer such as breast cancer genes 1 and 2 (BRCA-1, BRCA-2), RNAs, proteins such as prostate-specific antigen (PSA) or circulating tumor DNA (ct-DNA)." (PMID 34208595, 2021). "For example, germline heterozygous mutations in genes directly implicated in HR—BRCA1, BRCA2, PALB2, RAD51C and RAD51D—increase the risk of ovarian and breast cancer." (PMID 33923105, 2021). "The first study on breast cancer risk was a case-control study including 1054 pairs of women with BRCA1 mutation and 326 pairs of women with BRCA2 mutation." (PMID 33996049, 2021). "Following the discovery of BRCA1 and BRCA2, several breast cancer genes with various degree of penetrance were identified." (PMID 33649982, 2021). "Nevertheless, within the cohort of young BRCA-mutated breast cancer patients, the prognostic implications of carrying a germline BRCA1 or BRCA2 pathogenic variant as well as potential differences according to hormone receptor status remained largely undefined." (PMID 33579978, 2021). "The breast cancer susceptibility proteins BRCA1 (also known as FANCS), BRCA2 (FANCD1), and RAD51 (FANCR) and its paralogs, including XRCC2 (FANCU) and XRCC3, all serve a function in homologous recombination repair (HRR)." (PMID 33625522, 2021). "We recommend that a simple test for Polish founder mutations in BRCA1, BRCA2, PALB2 and CHEK2 should be offered to all male breast cancer patients in Poland." (PMID 34461861, 2021). "Recent case-control studies in Caucasian women have reported relative risks of breast cancer for the BRCA1 and BRCA2 genes of 5.9–10.6-fold and 3.3–5.9-fold, respectively, which were lower than the magnitude of breast cancer risks estimated in this study." (PMID 34606182, 2021). "The estimated cumulative risk of breast carcinoma for male BRCA1 mutation carriers at age 70 years was 1.2% and for BRCA2 mutation carriers, 6.8%." (PMID 34356066, 2021). "Around 5% of all breast carcinoma patients and 12 to 18% of breast cancer in young patients are associated with Hereditary Breast and Ovarian Cancer Syndrome, which are caused by BRCA1 or BRCA2 mutations." (PMID 34944094, 2021). "To explore a possible genotype–phenotype correlation, we performed additional analyses of 203 unrelated families with P/LPVs in BRCA2 and 177 cases of female breast cancer (FBC) in carriers of P/LPVs in BRCA2." (PMID 33891299, 2021). "During the 1990’s, germline variants in the breast cancer susceptibility genes BRCA1 and BRCA2 were first described as showing increased risk for HBOC." (PMID 32039725, 2020). "Similar results were also observed with clinical benefit of olaparib in BRCA2 mutated pancreatic cancer and in BRCA1/2 mutated breast cancer." (PMID 32778095, 2020). "Early studies estimated that RRSO provided approximately a 50% reduction in the risk of breast cancer in women with BRCA1 and BRCA2 mutations, particularly if performed before age 45 years." (PMID 32337493, 2020). "About 5–10% of breast cancers can be linked to gene mutations inherited from one’s mother or father, such as BRCA1 or BRCA2 mutations." (PMID 32210163, 2020). "Breast cancer (BC) in patients with germline mutations of BRCA1/BRCA2 are associated with benefit from drugs targeting DNA damage response (DDR), but they account for only 5–7% of overall breast cancer." (PMID 32719318, 2020). "Genetic predisposition reportedly accounts for 5 to 10% of breast cancers, notably through alterations of the BRCA1 and BRCA2 genes." (PMID 32650744, 2020).